GLB1 (galactosidase beta 1)
Diseases named in the same sentence as GLB1 in open-access papers (continued):
Sharing a sentence is not in itself a finding about the gene and the disease.
cancer (14 papers, 2013 to 2025). A tumor composed of atypical neoplastic, often pleomorphic cells that invade other tissues. "GLB1 is a lysosomal exoglycosidase that catabolizes glycoconjugates and has been linked to cancer cell senescence." (PMID 36936948, 2023). "AKR1C1, CYP27A1, CYP2C9, GLB1, HMGCS2, and PLPP1, all six LMRGs, have been implicated in the genesis and progression of cancer." (PMID 36936948, 2023). "Increased GLB1 after neoadjuvant ADT occurs primarily among more clinically favorable intermediate grade cancers and enrichment of the phenotype occurs in a temporally prolonged fashion." (PMID 28234906, 2017). "Our data shows that GLB1 expression after ADT depends on the Gleason score of the cancer in that significant induction of GLB1 was only noted in intermediate PCa and not in high grade disease." (PMID 28234906, 2017). "Increased GLB1 is a valuable marker in formalin-fixed paraffin-embedded (FFPE) tissues for the senescence-like phenotype and associates with improved cancer outcomes." (PMID 25876105, 2015). "Vectra allows a comparison of GLB1 expression in individual cells within cancer, HGPIN, or benign epithelium." (PMID 25876105, 2015). "For example, GLB1 are abundant in cancer, especially in DLD-1 cells engineered to over-express certain oncogenes." (PMID 23382867, 2013). "GLB1 is a lysosomal exoglycosidase involved in the catabolism of glycoconjugates and could affect the senescence of cancer cells." (PMID 35127693, 2021). "Accumulated evidences demonstrated that GLB1 is involved in cell senescence and cancer development." (PMID 27489354, 2016). "Cancer also displayed less heterogeneity of GLB1 when compared to benign prostate tissue." (PMID 25876105, 2015). "However, the remaining eight cancer-specific DESPGs of GLB1, HSPA5, PDIA3, GNRH1, IFNGR2 ADAM9, TPST2, and TAC4) were not reported in any researches, which could be potential novel prognostic biomarkers in corresponding tumors." (PMID 31824949, 2019). "Indicative of its tumor suppressive nature, GLB1 was found to be highest in HGPIN, known to contain senescent cells compared to benign and cancer tissues." (PMID 25876105, 2015). "In PC treated with neoadjuvant ADT, GLB1 expression increased in intermediate Gleason score (GS 6–7; p = 0.001), but not high grade (GS 8–10) cancer." (PMID 28234906, 2017). "Increased GLB1 protein, especially in cancer cell lines, may therefore not always be specific for senescence." (PMID 25876105, 2015).
infection (7 papers, 2005 to 2025). The state of being infected such as from the introduction of a foreign agent such as serum, vaccine, antigenic substance or organism. "Nonetheless, during the early post-infection phase, Glb1-/- mice exhibited a slightly delayed T cell response and an elevated activation state of CNS microglia compared to C57BL/6 wildtype mice." (PMID 40270964, 2025). "Overall, these data indicate a delayed antiviral T cell response in Glb1-/- compared to Glb1+/+ mice after TMEV infection but a slightly enhanced T cell infiltration into the CNS due to GM1 lysosomal storage in older animals." (PMID 40270964, 2025). "In summary, we observed a delayed induction of the immune response in Glb1-/- compared to Glb1+/+ mice during TMEV infection." (PMID 40270964, 2025). "This suggests that Glb1-/- mice mount a delayed inflammatory response to TMEV-infection, which is still present at 14 dpi in the brain." (PMID 40270964, 2025). "In this study, we show that Arabidopsis mutants with altered levels of phytoglobin 1 (Glb1) have a higher survival rate than wild type (WT) after infection with F. oxysporum, although all the genotypes analyzed exhibited a similar fungal burden." (PMID 37507861, 2023). "However, in the early phase post infection, Glb1-/- mice displayed a slightly delayed T cell response as well as an increase in the number and activation of CNS microglia." (PMID 40270964, 2025). "Glb1-/- mice developed clinical signs of GM1 LSD at an age of 14-15 weeks (9-10 weeks post infection), which were not altered by TMEV infection." (PMID 40270964, 2025). "At 98 dpi, only Glb1-/- but not Glb1+/+ mice showed an increased number of CD3+ T cells after TMEV infection (Figure 3D1-D5)." (PMID 40270964, 2025). "For this purpose, Glb1-/- and wildtype control mice (both C57BL/6 background) were intracerebrally infected with the BeAn strain of Theiler’s murine encephalomyelitis virus (TMEV) at the age of 5 weeks and sacrificed 4, 7, 14 and 98 days post infection, respectively." (PMID 40270964, 2025).
tumor (6 papers, 2002 to 2025). "In contrast, GLB1 showed increased expression in primary tumor tissues compared with the resection margins." (PMID 40141206, 2025). "In the epithelial (tumor) compartment, GLB1 staining was expressed at higher levels, mean intensity 3.6 vs 4.3 (p = 0.02) in ADT-exposed prostate samples compared to controls." (PMID 28234906, 2017). "A wide range of GLB1 expression occurred in months 1–5 suggesting a range of tumor responses to ADT." (PMID 28234906, 2017). "An increase in nuclear GLB1 expression was also found in tumor specimens of lower stage (p = 0.008)." (PMID 25876105, 2015). "Furthermore, β-galactosidase/GLB1 activity increased following glycolysis inhibition in stem cell-like tumor subpopulations, further corroborating an induction of senescence." (PMID 37420311, 2023). "We ensured that GLB1 could inhibits the OS cells to proliferate and invasion, which means GLB1 may inhibits the growth and metastasis of OS tumor tissue in OS invalids." (PMID 36313783, 2022).
neurological disease (4 papers, 2020 to 2022). "At the age of 3.5 to four months, Glb1−/− mice developed a neurologic disorder worsening until the age of 7.5 to eight months." (PMID 32252429, 2020).
dysostosis (3 papers, 2020 to 2021). A group of disorders in which the skeletal involvement is predominantly manifested as abnormalities of individual bones or in a group of bones. "Knowledge of the natural history and the genotype‐phenotype correlation of GLB1‐related conditions associated with the various types of dysostosis multiplex will be essential to inform the design and choice of outcomes in future clinical trials." (PMID 34258138, 2021). "W273L and T500A are the most frequently observed GLB1 variants in patients with a Morquio-like dysostosis multiplex." (PMID 33266180, 2020). "Central, subcortical periventricular, or cerebellar dysmyelination/hypomyelination was exclusively observed in these three patients with mild GLB1‐related dysostosis." (PMID 34258138, 2021). "There is also limited knowledge about the pattern and extent of the Morquio‐specific dysostosis multiplex in cases with MBD plus and how it overlaps with mild GLB1‐related dysostosis." (PMID 34258138, 2021). "Patients with GLB1‐related mild dysostosis had corneal clouding (P17) and hepatosplenomegaly (P15, P17)." (PMID 34258138, 2021). "With the aim to further describe patterns of MBD‐related dysostosis multiplex, we analyzed clinical, biochemical, and genetic features in 17 cases with GLB1‐related dysostosis multiplex living and diagnosed in Brazil." (PMID 34258138, 2021). "About 14 of the 17 patients had three or more radiological/clinical findings characteristic of the Morquio type of dysostosis multiplex and thus met the criteria for GLB1‐related MBD (P 2‐14, P16)." (PMID 34258138, 2021). "However, while GALNS‐related Morquio A and GLB1‐related MBD share similar patterns of dysostosis multiplex, skeletal manifestations are usually milder in MBD when compared to typical Morquio‐A disease." (PMID 34258138, 2021).
metabolic disorders (3 papers, 2017 to 2025). "Deficiency of the enzyme β‐galactosidase due to variants in the GLB1‐gene is associated with metabolic disorders: Morquio B and GM1‐gangliosidosis." (PMID 36341176, 2022). "GLB1 (chromosome 23) was observed in the flanking region of an outlier in the test across all four breeds as well as in two pairwise tests (Buhund–Norrbottenspets; Icelandic Sheepdog–Norrbottenspets); mutations in this gene have been linked to metabolic diseases and hypermobile joints." (PMID 28570553, 2017). "In this study, we identified four key genes, including FADS1, FADS2, GLB1, and PNPLA3, associated with both metabolic disorders and inflammation in MAFLD through bioinformatics methods." (PMID 41007773, 2025).
neurodegenerative disease (3 papers, 2020 to 2025). A disorder of the central nervous system characterized by gradual and progressive loss of neural tissue and neurologic function. "This study revealed that the five biomarkers, GLB1, ARSB, ASAH1, HEXB, and PSAP are all enriched in the lysosomal, chemokine, oxidative phosphorylation, and neurodegenerative disease pathways." (PMID 40534738, 2025).
genetic diseases (2 papers, 2020 to 2025). "Among genes within this region, only two genes, CRTAP and GLB1, have been reported to be associated with genetic diseases, both of which are manifested in an autosomal recessive manner." (PMID 32922437, 2020).
kidney disease (1 paper, 2019). "Notably, among these abnormally expressed proteins, 19 proteins were reported as kidney disease markers (Ada, Ambp, Anxa1, B2m, Camp, Col1a1, Cp, Ggt1, Glb1, Lgfbp7, Lifr, Lpl, Plau, Ptgds, S100a8, Serpinc1, Serpina3k, Tff1, and Vtn) (highlight in green)." (PMID 31708494, 2019).
psychiatric disorder (1 paper, 2018). A disorder characterized by behavioral and/or psychological abnormalities, often accompanied by physical symptoms. "Whilst CRTAP and GLB1 have not previously shown association with psychiatric disorders, both genes are members of the CNTN1 PPI subnetwork." (PMID 29317602, 2018).
retinopathies (1 paper, 2025). "However, the exact pathogenic mechanism behind GS dysregulation in MCs in retinopathies and whether these changes contribute to visual impairment in the Glb1−/− model require further investigation." (PMID 40804287, 2025).
GLB1 also shares sentences with these, for which no sentence is quoted: GM2 gangliosidosis (2 papers); Sandhoff disease (2); Tay-Sachs disease (2); acne (1); Airway obstruction (1); allergic disease (1); Alzheimer disease (1); amyotrophic lateral sclerosis (1); Brain atrophy (1); breast carcinoma (1); chronic obstructive pulmonary disease (1); congenital glycosylation disorders (1); Costello syndrome (1); COVID-19 (1); developmental delay (1); endometrial carcinoma (1); epilepsy (1); Epileptic encephalopathy (1); Fabry disease (1); Gaucher disease type II (1); hematological tumors (1); Hepatic steatosis (1); Hermansky-Pudlak syndrome (1); HIV-1 infection (1); hyperparathyroidism (1); Kidney (1); Krabbe disease (1); Kyphoscoliosis (1); Leber congenital amaurosis (1); Lipid storage disease (1).
A further 15 diseases each share a sentence with GLB1 in 1 paper.